INHBA (inhibin subunit beta A)
Diseases named in the same sentence as INHBA in open-access papers (continued):
Sharing a sentence is not in itself a finding about the gene and the disease.
ovarian carcinoma (19 papers, 2015 to 2025). A malignant neoplasm originating from the surface ovarian epithelium. "Li and colleagues showed that targeting INHBA in ovarian cancer cells is implicated in hindering the activation of stromal fibroblasts." (PMID 38329386, 2024). "By evaluating the levels of transcripts encoding IL‐6 and INHBA in tumour biopsies from ovarian cancer patients (n = 307) using the cBioPortal website, we found a significant association between the expression of these genes." (PMID 31436048, 2020). "The role that INHBA played in cancers was found to be associated with activin A levels in colorectal cancer, prostate cancer, and ovarian cancer." (PMID 32647495, 2020). "INHBA has been reported to be implicated in the progression of multiple types of cancer including ovarian cancer (OC)." (PMID 31827640, 2019). "This is similar to the findings in a previous report in which subsets of CAFs with high expression of INHBA lead to the immunosuppressive microenvironment that prevents the infiltration of CD8+T cells in ovarian cancer." (PMID 41008625, 2025). "Spatiotemporal analyses of patient-matched primary, metastatic, and recurrent ovarian carcinomas revealed that aggressive metastatic tumors enriched in INHBA(+) CAFs were also enriched in regulatory T cells (Tregs)." (PMID 38360876, 2024). "The main mechanism by which INHBA/Activin A contribute to ovarian cancer progression was thought to be the induction of epithelial-mesenchymal transition." (PMID 38360876, 2024). "qRT-PCR confirmed a higher expression of INHBA in 781T CAFs and PCAFs compared to the epithelial ovarian cancer cell lines OVCAR3 and Kuramochi and peripheral blood mononuclear cells (PBMCs)." (PMID 38360876, 2024). "Together, these data suggest a possible immunoregulatory function of INHBA(+) fibroblasts in human ovarian cancer." (PMID 38360876, 2024). "Collectively, our study identified an INHBA(+) subset of immunomodulatory pro-tumoral CAFs as a potential therapeutic target in advanced ovarian cancers which typically show a poor response to immunotherapy." (PMID 38360876, 2024). "Recent studies have shown that INHBA expression is elevated in malignant tumors such as gastric, esophageal, and ovarian cancers." (PMID 37940978, 2023). "Studies showed that overexpression of INHBA is positively correlated with poor prognosis in esophageal, prostate and ovarian cancer." (PMID 34476008, 2021). "They further revealed that INHBA knockdown hampers the tumorigenesis in an ovarian cancer xenograft model by suppressing the activation of stromal fibroblast." (PMID 34346300, 2021). "In the present study, we demonstrated that INHBA mRNA and protein were overexpressed in ovarian cancer (OC) tissues, and INHBA expression significantly increased with the advance of serous ovarian cancer (SOC) pathological grades and clinical stages." (PMID 31827640, 2019). "Overall, our findings suggest a significant contributory role of PITX2 in promoting invasive behaviour of ovarian cancer cells through up-regulation of TGFB/INHBA." (PMID 26298390, 2015). "The involvement of activin-A, the homodimer form of INHBA, in inducing invasion leading to epithelial ovarian cancer progression (apart from GCT) has been demonstrated for the first time in this study." (PMID 26298390, 2015). "INHBA+ cancer-associated fibroblasts drive SMAD2-dependent PD-L1 expression and promote regulatory T-cell differentiation in advanced ovarian cancer, nominating INHBA protein/RNA and CAF-PD-L1 as tissue surrogates of TGF-β superfamily–linked immune suppression." (PMID 41181126, 2025). "However, our study shows that the mechanism by which INHBA/Activin A contribute to ovarian cancer progression is different than previously thought." (PMID 38360876, 2024). "We found that INHBA mRNA was expressed exclusively in CAFs in human HGSOC and the BR-luc syngeneic mouse ovarian cancer model." (PMID 38360876, 2024).
ovarian carcinoma (continued). "PITX2-induced INHBA expression (p < 0.01) contributed to EMT in both normal and ovarian cancer cells." (PMID 26298390, 2015). "The TGF‐β superfamily member activin, a dimer of the gene products of INHBA and/or INHBB, has been implicated in immune cell maturation and recruitment, but its immune impact within epithelial ovarian cancer (EOC) is not well characterized." (PMID 39248018, 2024).
colorectal cancer (15 papers, 2006 to 2026). A primary or metastatic malignant neoplasm that affects the colon or rectum. "Previous studies have shown that besides being associated with cell proliferation and migration, the INHBA gene is overexpressed in various tumors, such as colorectal cancer, esophageal cancer, and nasopharyngeal cancer." (PMID 34968391, 2021). "Recently, Xiao and colleagues revealed that 10 mmol/L of metformin, an oral antihyperglycemic used to treat type 2 diabetes mellitus, attenuates the expression of INHBA and inhibits the proliferation of colorectal cancer cells." (PMID 38329386, 2024). "As the subunit of activin A and inhibin, INHBA was reported highly expressed in multiple human cancers, including gastric cancer, colorectal cancer, esophageal adenocarcinoma, urothelial carcinoma, and lung cancer." (PMID 36304286, 2022). "For instance, high INHBA expression promoted malignant biological behavior by activating the TGF-β pathway in colorectal cancer and predicted the patients' prognosis." (PMID 36304286, 2022). "In conclusion, INHBA is a novel protein regulating cellular senescence and immune evasion in colorectal cancer." (PMID 34476008, 2021). "INHBA gene is overexpressed in different kinds of cancer, such as colorectal cancer, pancreatic cancer, and lung cancer, and promotes cell proliferation, invasion, metastasis and chemoresistance in cancer cells." (PMID 30746900, 2019). "In fact, it has been reported recently that INHBA is over-expressed in stage IV colorectal cancer." (PMID 16584549, 2006). "It has been reported that the expression of INHBA is upregulated in colorectal cancer tissues, which is strongly related to vascular cancer thrombus, vascular wall invasion and lymph node metastasis, suggesting that a high expression of INHBA may mainly participate in the evolution of colon cancer." (PMID 36984496, 2023).
colon cancer (13 papers, 2019 to 2025). "Previously, it was shown that INHBA and CCL19 exhibit opposite modes of expression in colon cancer, with INHBA being upregulated while CCL19 is concurrently downregulated." (PMID 38329386, 2024). "Apart from SPARC, the other genes correlating with immune infiltration included SPOCK1 and INHBA which were highly correlated with CAFs in colon cancer, as well as TUBB (correlations with myeloid dendritic cells in thymoma)." (PMID 36604669, 2023). "INHBA enhances the proliferation, migration, and invasion of colon cancer cells by upregulating VCAN." (PMID 35216189, 2022). "The results also supported that SPP1, COL11A1, ADAM12, and INHBA expressions were significantly higher in colon cancer tissues compared to that of the normal tissues in accordance with our previous study." (PMID 30746900, 2019). "In addition, high expression of INHBA is thought to promote the proliferation of colon cancer cells." (PMID 37675100, 2023). "INHBA was identified as an independent risk factor for both OS and DFS in colon cancer." (PMID 37377935, 2023). "In addition, INHBA has been proven to be a prognostic factor for patients with colon adenocarcinoma, and the expression of INHBA in colon cancer is significantly correlated with the stage of tumor lymph node metastasis (TNM)." (PMID 36984496, 2023). "Likewise, INHBA plays an immunomodulatory role in colon cancer, and BRIP1 is related to the susceptibility of colon cancer." (PMID 33836755, 2021). "We found that SPP1, VIP, COL11A1, CA2, ADAM12, INHBA could provide great significant prognostic value for colon cancer." (PMID 30746900, 2019). "The inverse relationship between INHBA and hsa-miR-375 in our study suggests that restoring the levels of hsa-miR-375 could potentially suppress INHBA activity, offering a therapeutic approach to inhibit tumor progression in colon cancer." (PMID 40426863, 2025). "The expression levels of INHBA and JAG2 in colonic epithelial cell line were remarkably lower than that in colonic cancer cell lines." (PMID 34103052, 2021). "The expression levels of INHBA and JAG2 in colonic cancer cell lines (CACO-2, HT29, SW480 and HCT116) were significantly higher than that in colonic epithelial cell line (NCM460)." (PMID 34103052, 2021). "In order to verify the reliability and accuracy of our results, we identified the expression levels of INHBA and JAG2 in CCa tumor tissues, adjacent tissues, human colonic epithelial cell line and colonic cancer cell lines." (PMID 34103052, 2021).
colon adenocarcinoma (11 papers, 2019 to 2025). "INHBA was found to be a novel mediator regulating cellular senescence and immune evasion and as a prognostic predictor for patients with colon adenocarcinoma, consistent with our findings of INHBA as a potential biomarker." (PMID 37446311, 2023). "Inhibin β A (INHBA) is a member of Transforming Growth Factor β superfamily, whose increased expression was shown in colon adenocarcinoma cells with prognostic significance." (PMID 34824625, 2021). "INHBA is a prognostic predictor in patients with colon adenocarcinoma." (PMID 37940978, 2023). "The C26 model is a well-described model of CC caused by subcutaneous implantation of colon adenocarcinoma cells and is associated with elevated levels of circulating ActA, partially due to high tumoral expression of INHBA (data not shown)." (PMID 35406681, 2022). "Furthermore, survival analyses based on gene expression (TCGA & GTEx profile) and mutational status (TCGA COAD & Pan‐cancer datasets) for colon adenocarcinoma identified CDKN2A, INHBA increased expression, and CDKN2A and TCF7L2 mutations as predictors of bad prognosis in metastatic patients." (PMID 40658092, 2025). "The analysis revealed that only high INHBA expression robustly predicted shortened OS and DFS in patients with colon adenocarcinoma (COAD)." (PMID 41449244, 2025).
melanoma (11 papers, 2016 to 2025). A malignant, usually aggressive tumor composed of atypical, neoplastic melanocytes. "Increased TGFβ1 signaling-associated downstream target genes such as TGFB1 and INHBA were observed in PGC1α silenced melanoma and lung adenocarcinoma cells." (PMID 35897813, 2022). "To evaluate a possible interaction of KLK8 with Activin-A in vivo, we assessed its correlation with INHBA expression in human melanoma." (PMID 40064965, 2025). "Here, sustained INHBA expression or acute treatment of YUMM3.3 melanoma cells with recombinant Activin-A enhanced STAT1 phosphorylation by IFN-γ but interfered with cytostatic IFN-γ signaling in vitro without further upregulating IFN target genes." (PMID 38304252, 2023). "Despite an overall increase in T cell infiltration, human melanoma with high levels of INHBA had a two-fold lower CD8 to CD4 ratio." (PMID 38304252, 2023). "Average INHBA mRNA levels in the TCGA dataset of human melanoma (SKCM) were also comparable in primary and metastatic tumors." (PMID 35580932, 2022). "We analyzed the expression of the Activin-A encoding gene INHBA in melanoma patients and the influence of its gain- or loss-of-function on the immune infiltration and growth of BRAF-driven YUMM3.3 and iBIP2 mouse melanoma grafts and in B16 models." (PMID 35580932, 2022). "To address whether INHBA expression correlates with increased IFN signaling also in human melanoma, we analyzed the Melanoma PanCancer database." (PMID 38304252, 2023). "In addition, we show that Activin-A/INHBA expression correlates with anti-PD1 therapy resistance in melanoma patients and impairs the response to dual anti-cytotoxic T-Lymphocyte associated protein 4/anti-PD1 treatment in preclinical models." (PMID 35580932, 2022). "To validate whether INHBA-induced tumor growth is mediated by the inhibition of adaptive antitumor immunity across multiple melanoma models, we transplanted tumor cells into immunodeficient Rag1-/- mice." (PMID 35580932, 2022). "Finally, we assessed INHBA expression in melanoma patients who received immune checkpoint therapy and tested whether it impairs the response in preclinical models." (PMID 35580932, 2022). "The results showed that INHBA mRNA expression was upregulated in bladder, breast, cervical, colorectal, esophageal, gastric, head and neck, ovarian, and pancreatic cancers and sarcoma with respect to normal tissues, whereas INHBA was downregulated in kidney cancer, leukemia, and melanoma." (PMID 36304286, 2022). "Here, we used the syngeneic mouse melanoma model YUMM3.3 and single-cell RNA sequencing (scRNA-seq) analysis to interrogate the changes induced by INHBA overexpression in tumor cells." (PMID 38304252, 2023). "In melanomas, genes coordinately expressed with GPC6 were largely those involved in cell adhesion and migration including INHBA, PDGFC, PDGFRA, PPAP2B, SPRX2, TCF4, and TNFAIP6 and ZEB1." (PMID 31199813, 2019). "Meanwhile, HLA-DRA, INHBA, DKK1, CTGF, PMP22, FLRT3 and NRCAM genes, upregulated in G10, were described as overexpressed in invasive melanomas." (PMID 27206673, 2016). "In at least two of these, KLK8 expression increased in the presence of Activin-A, even though KLK8 and INHBA were not consistently co-expressed in the human melanoma cohort examined here." (PMID 40064965, 2025). "In all melanoma models examined, and irrespective of their BRAF status, INHBA expression reduced the frequency of intratumoral CTLs and NK cells." (PMID 35580932, 2022).
lung adenocarcinoma (10 papers, 2019 to 2025). A carcinoma that arises from the lung and is characterized by the presence of malignant glandular epithelial cells. "Further evidence for TGFB2 versatility is that 2 TGFB2 ligand mutations Cys246Tyr and Cys407Ser share a lung adenocarcinoma phenotype with a mutation in β8Cys@1 of INHBA Cys244Tyr." (PMID 36214621, 2022). "High expression of INHBA (inhibin beta A subunit) linked with cell proliferation in lung adenocarcinoma, but this gene might be associated with cell proliferation in pituitary prolactinoma." (PMID 33709028, 2021). "In primary lung adenocarcinoma, it was found that expression levels of INHBA were 3 times higher than in normal lung tissue." (PMID 41463203, 2025). "It has been confirmed that INHBA was overexpressed in lung adenocarcinoma, which promoted tumor proliferation and correlated with poor outcomes in stage I disease." (PMID 35236827, 2022). "According to previous studies, the upregulation of INHBA mRNA expression occurs after treatment with the methyltransferase inhibitor, 5-aza-2’-deoxycytidine, in esophageal adenocarcinoma and lung adenocarcinoma cell lines." (PMID 35216189, 2022). "Exceptions were head and neck and esophagogastric cancers that had high expression of INHBA and lung adenocarcinoma and renal clear cell carcinoma that had high expression of INHA." (PMID 33819300, 2021). "Upregulation of INHBA expression promotes cell proliferation and predicts poor survival in patients with lung adenocarcinoma." (PMID 31827640, 2019). "In addition, INHBA was found to promote cancer progression in lung adenocarcinoma by accentuating the proliferation of tumor cells." (PMID 38329386, 2024). "INHBA overexpression may be affected by promoter methylation in lung adenocarcinoma and esophageal adenocarcinoma." (PMID 35216189, 2022).
pancreatic cancer (9 papers, 2016 to 2024). "INHBA is a susceptibility gene for pancreatic cancer that is involved in the TGF-β signaling pathway and was edited by AS in our ONT analysis." (PMID 35909892, 2022). "In line with our findings, Lonardo and colleagues showed INHBA to be vital for the ability of pancreatic cancer stem cells to self-renew and maintain their stemness." (PMID 38329386, 2024). "Next, the immune‐related prognosis model was established by the expression of immune‐related genes MMP14 and INHBA in pancreatic cancer." (PMID 35150061, 2022). "Effects of MCM and the immune genes MMP14, INHBA on the invasion of pancreatic cancer cells were evaluated by trans‐well assay." (PMID 35150061, 2022). "Knock‐down of MMP14 and INHBA inhibited invasion of pancreatic cancer." (PMID 35150061, 2022). "Knockdown immune‐related genes MMP14 or INHBA decreased the invasion of pancreatic cancer cells, which could also be promoted by MCM." (PMID 35150061, 2022). "However, among above secreted protein genes, only INHBA is dramatically increased in both pancreatic tumor datasets compared to normal tissues." (PMID 26975989, 2016). "Treating pancreatic cancer cells PANC1 with macrophage M2‐conditioned medium lead to up‐regulated MMP14 and INHBA expression, suggesting macrophages M2 up‐regulate these genes and can be used as risk predictors." (PMID 35150061, 2022). "Then, we applied macrophage conditioned medium to culture pancreatic cancer cell line PANC1, detected the expression of MMP14 and INHBA by qRT‐PCR and Western blot methods." (PMID 35150061, 2022).
preeclampsia (9 papers, 2012 to 2024). Preeclampsia is a hypertensive disorder of pregnancy that is characterized by new-onset hypertension with proteinuria presenting after 20 weeks of gestation, and depending on mild or severe forms may initially present with severe headache, visual disturbances, and hyperreflexia. "INHBA encodes subunits of activin and inhibin and has been associated with the development of preeclampsia in several studies." (PMID 35880174, 2022). "We also observed high DMC density regions in genes for which placental DNAm and/or expression differences have been associated with preeclampsia, including INHBA, JUNB, TEAD3, NDRG1, and CGA." (PMID 33407091, 2021). "In summary, we identified three key inflammation-associated genes, namely INHBA, OPRK1, and TPBG, which can be used as potential genetic biomarkers for preeclampsia prediction and treatment, and established a nomogram as a predictive model." (PMID 35880174, 2022). "We further analyzed INHBA, OPRK1, and TPBG, which played a crucial role in the development of preeclampsia." (PMID 35880174, 2022). "The expression of INHBA, OPRK1, and TPBG showed significant differences between preeclampsia and non-preeclampsia samples." (PMID 35880174, 2022). "FLT1, LEP, INHA and ENG genes were identified according to the literature, however, we also found other genes as FLNB, INHBA, NDRG1 and LYN highly significant but underexplored during normal pregnancy or preeclampsia." (PMID 24219996, 2013). "The authors found that the INHBA gene together with the OPRK1 and TPBG genes are key inflammation-related genes that affect the course of pregnancy (the expression of INHBA and TPBG genes in complicated preeclampsia pregnancy is higher, and the OPRK1 gene is lower, compared with normal pregnancy)." (PMID 37511900, 2023). "Subsequently, we analyzed the expression of INHBA, OPRK1, and TPBG in preeclampsia placental tissue and non-preeclampsia placental tissue." (PMID 35880174, 2022). "Supported by our data, activin A (INHBA) and inhibin A (INHA), but not inhibin B (INHB), are increased in patients with preeclampsia." (PMID 34970543, 2021).